MAGEA3 (MAGE family member A3)
Diseases named in the same sentence as MAGEA3 in open-access papers (continued):
Sharing a sentence is not in itself a finding about the gene and the disease.
hepatocellular carcinoma (13 papers, 2002 to 2022). A malignant tumor that arises from hepatocytes. "Similarly, a recent study has implicated the role of MAGEA3 in hepatocellular carcinoma (HCC) and suggested as a novel therapeutic avenue of targeting MAGEA3 for HCC." (PMID 35964339, 2022). "In hepatocellular carcinoma (HCC), LINC01234 was involved in proliferation and chemoresistance through the MAGEA3/LINC01234/miR-31-5p axis." (PMID 35765893, 2022). "Our qRT-PCR analyses revealed that the mRNA expression levels of MAGEA-3, MAGEA-1, p16, and p15 were significantly increased in the hepatocellular carcinoma HepG2 cell lines after treatment with 10 nM DAC for 72 h and that the RASSF1A and BRCA1 levels were unchanged." (PMID 24963497, 2014).
metastatic carcinoma (11 papers, 2010 to 2024). A carcinoma which has spread from the original site of growth to another anatomic site. "Interestingly, we identify MAGEA proteins, including MAGEA3, which is induced in a variety of metastatic cancers and has been targeted most recently in a phase-II clinical trial." (PMID 32719445, 2021). "Moreover, adoptive CD4+ T cell therapy using HLA-DPB1*0401 restricted TCR recognizing MAGEA3 has been proved to be effective in 17 patients with metastatic cancer and 4/17 patients treated with DPB1*0401 restricted TCR-T cells showed durable clinical response (1CR, 3PR)." (PMID 37287989, 2023).
colorectal cancer (9 papers, 2016 to 2025). A primary or metastatic malignant neoplasm that affects the colon or rectum. "In colorectal cancer (CRC), MAGEA3 has been reported as a colorectal cancer-related serological biomarker." (PMID 29678180, 2018). "Our in vitro experiments revealed a novel mechanistic insight: MAGEA3 specifically inhibits the expression and secretion of VEGF through the mTOR signaling pathway in colorectal cancer cells, while exhibiting minimal impact on other key angiogenic factors such as PDGF, FGF, and ANGPT2." (PMID 40342736, 2025). "Since MAGEA3 is reported to have exclusively high expression in tumors, we assessed its expression in both AOM/DSS-induced mouse models of colorectal cancer and human colorectal cancer cell lines and tissues." (PMID 40342736, 2025).
sarcoma (9 papers, 2015 to 2024). A usually aggressive malignant neoplasm of the soft tissue or bone. "Our 106-core tissue microarray staining has shown that not only the MAGEA3 gene, but also the encoded protein is expressed in this sarcoma subtype." (PMID 31096717, 2019). "Expression of HLA-A, HLA-DPB1, and lymphocyte marker LCK were analyzed in TCGA sarcoma subtypes to determine whether a significant loss of antigen presentation in UPS/MFS could limit efficacy of immunotherapies targeting MAGEA3." (PMID 31096717, 2019). "By comparison, the CCLE showed variable expression of MAGEA3 among a diverse number of sarcoma cell lines." (PMID 31096717, 2019). "MAGEA3 is an attractive immunotherapy target in multiple cancers, and its expression in sarcoma predicts that adoptive T cell therapies or cancer vaccines may be successfully applied in specific sarcoma subtypes that express this antigen." (PMID 31096717, 2019). "Of note, only one cell line (GCT) representing pleomorphic sarcomas was contained in the CCLE database, and that cell line shows high MAGEA3 expression." (PMID 31096717, 2019). "HLA-A mRNA expression and HLA-DPB1 mRNA expression were found to be significantly higher in UPS/MFS compared to other sarcomas, suggesting that efficacy of TCR-based immunotherapies targeting MAGEA3 may not be limited by loss of HLA expression." (PMID 31096717, 2019).
pancreatic cancer (8 papers, 2011 to 2023). "Overexpression of Melanoma associated antigen A3 (MAGEA3) is reported in certain pancreatic cancer (PCA) patients." (PMID 31287009, 2019). "The poor prognosis of patients is also reported to be associated with MAGEA3 expression in different cancers including pancreatic cancer." (PMID 31287009, 2019). "Most recently MAGEA3 was functionally characterized as having a pro-tumor role in experimental models of pancreatic cancer and HCC." (PMID 34166362, 2021). "The major objective of the current study was to investigate the functional role of MAGEA3 in pancreatic cancer cells (PCCs) growth and survival." (PMID 31287009, 2019). "Using overexpression (tet-on regulated system and constitutive expression system) and knockdown (by siRNA and shRNA) approach, we dissected the mechanistic role of MAGEA3 in pancreatic cancer pathogenesis." (PMID 31287009, 2019). "So, we thought to investigate the role of MAGEA3 in pancreatic cancer cells under GF-deprived condition using both monolayer (2D) culture model and spheroid (3D) model." (PMID 31287009, 2019). "Our study provides experimental evidence that suggests MAGEA3 is an important survival molecule for pancreatic cancer cells under metabolic and genotoxic stress conditions." (PMID 31287009, 2019). "a, b qPCR (a) and immunoblot (b) analysis showing the differential expression of MAGEA3 in different pancreatic cancer cell lines." (PMID 31287009, 2019). "We tried two siRNA sequences targeting MAGEA3 and both the siRNA were equally efficient to reduce MAGEA3 expression in BxPC3 pancreatic cancer cells." (PMID 31287009, 2019). "In the current study, we report the mechanistic role of MAGEA3 in pancreatic cancer cells (PCCs) growth and survival in the presence and absence of growth factor (GF)." (PMID 31287009, 2019). "MAGEA3 provides survival advantages to the pancreatic cancer cells in spheroid culture model." (PMID 31287009, 2019). "CCL2 is known to promote angiogenesis in different cancers; hence, MAGEA3-mediated CCL2 overexpression in pancreatic cancer cells might have also indirectly contributed to the overall tumor growth in vivo, which warrants further investigation." (PMID 31287009, 2019). "However, we observed a high level of MAGEA3 in BxPC3 pancreatic cancer cells." (PMID 31287009, 2019). "Hence, future studies in these aspects might elucidate the influence of common genetic aberrations on MAGEA3 function in pancreatic cancer cells." (PMID 31287009, 2019). "Thus, it cautious the strategy to overexpress molecules like MAGEA3 in pancreatic cancer cells, which will make them more immunogenic like in other cancers but may have a serious negative consequence." (PMID 31287009, 2019). "We observed almost undetectable level of MAGEA3 in AsPC1, MiaPaCa2, SW1990 and PANC1 pancreatic cancer cells both at mRNA and protein level." (PMID 31287009, 2019). "Indeed, our MAGEA DNA vaccine successfully elicits effective T cell activities against each antigen and effectively eliminates GemR tumor cells expressing high levels of MAGEA2, MAGEA3, and MAGEA10 in two distinct mouse models of pancreatic cancer." (PMID 37814317, 2023).
glioblastoma (7 papers, 2011 to 2021). The most malignant astrocytic tumor (WHO grade IV). "In glioblastomas, the growing list of candidate TAAs include the epidermal growth factor receptor (EGFR), tenascin-C (TNC), fatty acid binding protein 5 (FABP5), melanoma-associated antigen 3 (MAGEA3), glioma-expressed antigen 2 (GLEA2), and PHD finger protein 3 (PHF3)." (PMID 25944688, 2015).
colon carcinoma (6 papers, 2014 to 2023). "MAGEA3 is a proven tumor maintenance gene in lung, breast and colon cancer, where cell line viability was dependent on MAGEA3 expression and overexpression was capable of transforming human colonic epithelial cells." (PMID 34166362, 2021).
cutaneous melanoma (6 papers, 2019 to 2025). A primary melanoma arising from atypical melanocytes in the skin. "In GSE35640, including 56 skin cutaneous melanoma (SKCM) patients undergoing MAGEA3 immunotherapy, the low-risk group had a higher response rate than the high-risk group (59 vs. 19%)." (PMID 40670378, 2025). "Although MAGEA3-positive cutaneous melanoma patients were selected for this trial, they were not further selected based on immune landscape such as those defined here." (PMID 35964339, 2022).
cervical cancer (5 papers, 2017 to 2025). A primary or metastatic malignant neoplasm involving the cervix. "In contrast, inhibitory effect of MAGEs on apoptosis has also been reported: MAGEA3 was shown to promote proliferation while suppressing apoptosis of cervical cancer cells." (PMID 34788311, 2021).
myocarditis (5 papers, 2023 to 2025). Myocarditis is a condition that is characterized by inflammation of the heart muscle (myocardium). "We validated PS-TRACT on experimentally observed cross-reactive peptides, including tumoral and microbial epitopes, and the TTN peptide ESDPIVAQY which was found to be the off-tumor target in cases of fatal myocarditis in patients receiving TCR-T cells directed at the MAGEA3 epitope EVDPIGHLY." (PMID 40814001, 2025).
prostate carcinoma (5 papers, 2018 to 2022). A carcinoma that arises from epithelial cells of the prostate gland. "Protein lysates from LNCap prostate cancer cells and PANC-1 cells transfected with MAGEA3 overexpression construct (PANC1-MAGEA3) are used as positive control for MAGEA3 expression; β-actin is used as loading control." (PMID 31287009, 2019).
lung adenocarcinoma (4 papers, 2013 to 2024). A carcinoma that arises from the lung and is characterized by the presence of malignant glandular epithelial cells. "Cancer testis antigen (CTA) Melanoma Antigen Gene A3 (MAGEA3) were overexpressed in multiple tumor types, but the expression pattern of MAGEA3 in the serum of lung adenocarcinoma (LUAD) remains unclear." (PMID 38555374, 2024).
osteosarcoma (4 papers, 2021 to 2024). A usually aggressive malignant bone-forming mesenchymal neoplasm, predominantly affecting adolescents and young adults. "For lentivirus-mediated overexpression of MAGEA3 in osteosarcoma cells, full-length human MAGEA3 (NM_005362.3) was inserted into the pHBLV-CMV-MCS-3FLAG-EF1-ZsGreen-T2A-PURO lentiviral vector (Hanbio Biotechnology, Shanghai, China)." (PMID 36680568, 2023). "CD8+ T cells cross-primed by γδ T-MAGEA3 or DC-MAGEA3 showed robust but comparable cytotoxicity against diverse MAGEA3+ osteosarcoma cell lines when evaluated by the LDH release assay." (PMID 36680568, 2023). "Since osteosarcoma-specific antigens remain unknown, MAGEA3 was ectopically expressed in osteosarcoma cell lines." (PMID 36680568, 2023). "Osteosarcoma cell lines were transfected with MAGEA3 for the cytotoxicity assays." (PMID 36680568, 2023). "Among the five DE-ERSRGs, the Kaplan–Meier survival analysis suggested that osteosarcoma patients exhibiting high expression levels of BCL2, MAGEA3, MAP3K5, and TXNDC12 had significantly improved overall survival rates." (PMID 38229155, 2024). "CD8+ T cells were, respectively, co-cultured with γδ T-APCs, γδ T-IP, γδ T-MAGEA3 or DC-MAGEA3 before being co-cultured with MAGEA3-transfected or non-transfected osteosarcoma cells." (PMID 36680568, 2023).
squamous cell carcinoma (4 papers, 2012 to 2025). A carcinoma arising from squamous epithelial cells. "MAGEA3 is not expressed in adenocarcinoma but is expressed in squamous cell carcinoma (Pearson’s correlation with purity >0.1, q < 0.1), although MAGEA3 expression in the latter is negatively associated with CD8 T-cell infiltration." (PMID 27549193, 2016). "An active phase I clinical trial (NCT02285816) is assessing MG1-MAGEA3 with and without Ad-MAGEA3 in patients with incurable, advanced, or metastatic MAGE-A3-expressing solid tumors, including NSCLC (adenocarcinoma and squamous cell carcinoma), although results have not yet been reported." (PMID 40006732, 2025).
cutaneous squamous cell carcinoma (3 papers, 2020 to 2025). "Previous studies have shown that high MAGEA3 levels are associated with worse prognosis in cutaneous squamous cell carcinoma, malignant peripheral nerve sheath tumor, and other cancers." (PMID 40342736, 2025).
lymph node metastasis (3 papers, 2020 to 2024). "The result revealed that MAGEA3 is upregulated in GC and linked to poor OS and lymph node metastasis." (PMID 34970496, 2021). "In summary, our study revealed that MAGEA3 is associated with lymph node metastasis and correlates with immune infiltration levels in GC." (PMID 34970496, 2021). "The expression of MAGEA3 (P = 0.0021) and MAGEA4 (P < 0.0001) in serum exosomes were high expression and MAGEA3 level was positively correlated with lymph node metastasis of LUAD patients." (PMID 38555374, 2024). "The expression of MAGEA3 in N+ was higher than that in N0 (p < 0.05), which may indicate that MAGEA3 expression is correlated to lymph node metastasis." (PMID 34970496, 2021).
renal carcinoma (3 papers, 2016 to 2023). A carcinoma arising from the epithelium of the renal parenchyma or the renal pelvis. "Thus, MAGEA3 and PLAC1 may have some prognostic value, as observed in nonsmall lung cancer, renal carcinoma, or prostate adenocarcinoma." (PMID 27635108, 2016).
synovial sarcoma (3 papers, 2018 to 2021). "We found that MAGEA3 was highly expressed in UPS/MFS; the expression in these samples was significantly higher than in LMS (p < 0.05), DDLPS (p < 0.001), and synovial sarcoma (p < 0.001)." (PMID 31096717, 2019).
thyroid cancer (3 papers, 2020 to 2021). "Importantly, we provide confirmatory evidence that IGF2BP1 and MAGEA3 expression distinguishes ATC from poorly differentiated thyroid carcinoma." (PMID 32719445, 2021). "Exclusive expression of IGF2BP1 and MAGEA3 in ATC was initially validated by Western blotting in two ATC-derived cell lines (C643 and 8305C) and the individual samples of each thyroid cancer subtype comprised in the test cohort." (PMID 32719445, 2021). "Here, we reveal that IGF2BP1 and MAGEA3 are the first reliable protein and RNA markers of ATC, specifically distinguishing this malignancy from any other thyroid cancer of follicular origin, including PDTC." (PMID 32719445, 2021). "In addition, the analysis of MAGEA3, as a second promising marker, and MYC, as a well-known upregulated gene in high-grade thyroid carcinoma, was considered to be included into the study." (PMID 32719445, 2021).
Bladder tumor (2 papers, 2024). "The study reported that MAGEA3–9 members were expressed in 30%, 33%, 56%, and 54% of bladder tumors, respectively." (PMID 38254738, 2024).
leiomyosarcoma (2 papers, 2011 to 2019). An uncommon, aggressive malignant smooth muscle neoplasm, usually occurring in post-menopausal women. "For no other subtype was a survival difference observed based on MAGEA3 mRNA expression levels (leiomyosarcoma: detectable n = 29, undetectable n = 75; dedifferentiated liposarcoma: detectable n = 18, undetectable n = 40)." (PMID 31096717, 2019).
leukemia (2 papers, 2013 to 2023). A malignant (clonal) hematologic disorder, involving hematopoietic stem cells and characterized by the presence of primitive or atypical myeloid or lymphoid cells in the bone marrow and the blood. "It is intriguing to note that genes like MAGEA3 and ATP1A1, which indicated potential over expression in our study, are also over expressed in leukemia/lymphoma." (PMID 23343470, 2013).
chronic gastritis (1 paper, 2021). Inflammation of the stomach that is chronic in nature. "Serum concentration of MAGEA3 antibodies in the GC group (1.049 ± 0.384) was significantly higher than that of patients with chronic gastritis (0.546 ± 0.278) and healthy controls (0.412 ± 0.218) (F1 = 15.096, p < 0.01; F2 = 34.373, p < 0.01)." (PMID 34970496, 2021). "The MAGEA3-specific IgG was detected in 93 GC patients, 107 chronic gastritis patients, and 108 healthy controls by ELISA." (PMID 34970496, 2021).
colorectal adenoma (1 paper, 2018). An adenoma that arises from the colon or rectum. "Recent studies have shown that the number of long-chain RNAs, mRNAs KRTAP5–4 and MAGEA3 in serum-derived exosomes of colorectal adenoma patients is significantly different from healthy controls (AUC = 0.936)." (PMID 29558960, 2018). "In addition, recent studies have shown that the number of three long-chain RNAs (two mRNAs, KRTAP5–4, MAGEA3 and one lncRNA, BCAR) in serum exosomes of patients with colorectal adenoma is significantly different from healthy subjects, with the area under the ROC curve (AUC) being 0.936." (PMID 29558960, 2018).
Globozoospermia (1 paper, 2020). Any structural anomaly of the acrosome resulting in a round sperm head. "It remains uncertain whether variants in DNAH17 or MAGEA3 cause globozoospermia." (PMID 31985809, 2020).
liver cancer (1 paper, 2021). An epithelial or non-epithelial malignant neoplasm that arises from the liver. "Similarly, in 28 cancer cell lines that exhibit p53TC and p53TI signature (that includes cells from liver cancer and other cancer types) had relatively similar levels of C19MC miRNA expression, however, the MAGEA-3, MAGEA-6 and MAGEA-12 mRNAs were selectively upregulated in p53TI subset." (PMID 34135394, 2021).
sarcomatoid mesothelioma (1 paper, 2024). A diffuse malignant mesothelioma arising from the pleura and less often the peritoneum. "Conversely, several genes reported to be expressed in sarcomatoid mesothelioma were preferentially expressed in cluster 1: members of the MAGE family MAGEA1, MAGEA3, MAGEB2 and MAGEA6." (PMID 38212075, 2024).
stomach adenocarcinoma (1 paper, 2025). "Our comprehensive analysis reveals that MAGEA3 and MAGEA6 are epithelial-derived genes that are significantly associated with immune infiltration and tumor immune microenvironment remodeling in stomach adenocarcinoma." (PMID 41452900, 2025). "In this study, we systematically explored the role of epithelial-related differentially expressed genes (DEGs), particularly MAGEA3 and MAGEA6, in shaping the tumor immune microenvironment (TME) of stomach adenocarcinoma (STAD)." (PMID 41452900, 2025).
thyroid (1 paper, 2021). "In conclusion, this indicated the potential use of IGF2BP1, but also MAGEA3, expression for discriminating ATC from other thyroid malignancies, including PDTC." (PMID 32719445, 2021).
tongue cancer (1 paper, 2025). A malignant neoplasm affecting the tongue. "Among these, four genes (LY6K, ATAD2, CEP55, and MAGEA3) emerged as the most predictive of nodal spread specifically in tongue cancer." (PMID 41009820, 2025).
transitional cell carcinoma (1 paper, 2018). A malignant neoplasm arising from the transitional epithelium, usually affecting the urinary bladder, ureter, or renal pelvis. "This study aimed to evaluate the diagnostic value of outer dense fiber 4 (ODF4), melanoma-associated antigen A3 (MAGEA3), and MAGEAB4 mRNAs in transitional cell carcinoma (TCC), using a small amount of cell reverse transcriptase-polymerase chain reaction (RT-PCR) on urinary exfoliated cells." (PMID 28865418, 2018).